BTK (Bruton tyrosine kinase)
Diseases named in the same sentence as BTK in open-access papers (continued):
Sharing a sentence is not in itself a finding about the gene and the disease.
pancreatic adenocarcinoma (2 papers, 2018 to 2021). "BTK regulates the crosstalk between B cells and FcRγ+ TAMs in the TME and thus TAM-mediated immunosuppression of T cells in pancreatic adenocarcinomas, which can be reverted by treatment with ibrutinib or siRNA-mediated knockdown of BTK." (PMID 34778053, 2021). "BTK has also been described to regulate B-cell and macrophage mediated T-cell suppression in pancreatic adenocarcinoma." (PMID 29561760, 2018). "BTK signaling appears to play roles in multiple pathways in pancreatic adenocarcinoma." (PMID 29561760, 2018).
peanut allergy (2 papers, 2023). "In this open-label trial (NCT05038904), we evaluated the safety and efficacy of acalabrutinib, a BTK inhibitor that is FDA-approved to treat some B cell malignancies, in preventing clinical reactivity to peanut in adults with IgE-mediated peanut allergy." (PMID 37066249, 2023). "In this open-label trial, we evaluated the safety and efficacy of acalabrutinib, a BTK inhibitor that is FDA approved to treat some B cell malignancies, in preventing clinical reactivity to peanut in adults with peanut allergy." (PMID 37384412, 2023).
plasma cell disorders (2 papers, 2021 to 2025). "Zanubrutinib, a Bruton's tyrosine kinase (BTK) inhibitor, has shown efficacy in IgM-driven plasma cell disorders and was used in this case due to the patient's age, comorbidities, and high IgM burden." (PMID 41346800, 2025). "Bruton’s Tyrosine Kinase (BTK) has been a major target for B cell clonal disorders and its role in clonal plasma cell disorders is under active investigation." (PMID 34071917, 2021).
relapsing-remitting MS (2 papers, 2021 to 2022). "Compared with levels of BTK protein, we found higher levels of phospho-BTK in ex vivo blood memory B cells from patients with relapsing-remitting MS and secondary progressive MS compared with controls." (PMID 35852869, 2022). "Phase 2 trial of oral evobrutinib in relapsing-remitting MS showed a reduced relapse rate, and future studies could examine the effects of BTK inhibition on leptomeningeal inflammation in progressive MS." (PMID 33763241, 2021).
systemic sclerosis (2 papers, 2021 to 2023). A chronic disorder, possibly autoimmune, marked by excessive production of collagen which results in hardening and thickening of body tissues. "The idea to use BTK inhibitors in systemic sclerosis is generally based on the observation of the role of B cells (and myeloid cells) in the development of SSc." (PMID 37630981, 2023). "In a murine model of systemic sclerosis, BTKB66 (a new BTK inhibitor) treatment resulted in a reduction in skin fibrosis, collagen deposition, and decreased inflammatory cell infiltration in the skin." (PMID 37630981, 2023). "Effect of Bruton’s tyrosine kinase (BTK) inhibition on the affinity for topo I of topo I-reactive B cells and the development of fibrosis in the topo I-induced systemic sclerosis (SSc) model mice." (PMID 34854378, 2021).
tauopathy (2 papers, 2019 to 2023). Neurodegenerative disorders involving deposition of abnormal tau protein isoforms (tau proteins) in neurons and glial cells in the brain. "Next, we analyzed BTK levels in the Thy1-hTau.P301S tauopathy mouse model." (PMID 30758770, 2019).
uveitis (2 papers, 2018 to 2025). An inflammatory process affecting a part of or the entire uvea. "BTK inhibitors may cause uveitis through off-target immune modulation because BTK is expressed in myeloid cells and microglia; ibrutinib also inhibits ITK (important in T-cells) which could tilt immune responses and provoke ocular inflammation in susceptible individuals." (PMID 41568391, 2025). "According to recent publications, BTK is pathologically connected to uveitis by interfering immune cell differentiation and autoimmune responses." (PMID 30349554, 2018). "If severe or vision-threatening uveitis occurs, switching to an alternative BTK inhibitor might be an option (though cross-toxicity is not well documented)." (PMID 41568391, 2025).
acute leukemia (1 paper, 2021). A clonal (malignant) hematopoietic disorder with an acute onset, affecting the bone marrow and the peripheral blood. "Through this approach, we have discovered three novel KMT2A translocation partners in childhood acute leukemia—genes encoding tyrosine kinase BTK, ubiquitin-protein ligase PRPF19, and NUTM2A—gene of poorly known function." (PMID 34440129, 2021).
acute lung injury (1 paper, 2022). A condition of lung damage that is characterized by bilateral pulmonary infiltrates (pulmonary edema) rich in neutrophils, and in the absence of clinical heart failure. "Ibrutinib has potential therapeutic or protective effects against viral- and bacterial-induced acute lung injury (ALI), likely by modulating the Bruton tyrosine kinase (BTK) signaling pathway." (PMID 36362264, 2022).
acute promyelocytic leukemia (1 paper, 2022). An aggressive form of acute myeloid leukemia (AML), characterized by arrest of leukocyte differentiation at the promyelocyte stage, due to a specific chromosomal translocation t(15;17) in myeloid cells. "Having demonstratedJS25 as a potent inhibitor of BTK in biochemicalassays, we turned to its characterization in standard cell lines ofhematological cancers, related to an abnormal expression of BTK, includingBL, DLBCL, CLL, AML, and acute promyelocytic leukemia (APML)." (PMID 36407952, 2022).
ameloblastoma (1 paper, 2022). The most common odontogenic tumor, arising from the epithelial component of the embryonic tooth and usually affecting the molar-ramus region of the mandible or maxilla. "Since the exact role of BTK in the etiology of ameloblastoma has not been elucidated, further research is required to demonstrate the exact function of the gene in the disease." (PMID 36160115, 2022).
aneurysm (1 paper, 2025). Bulging or ballooning in an area of an artery secondary to arterial wall weakening. "This indicates that BTK plays a significant role in the inflammatory processes that contribute to aneurysm formation and rupture." (PMID 40507607, 2025).
anxiety disorder (1 paper, 2021). A category of psychiatric disorders which are characterized by anxious feelings or fear often accompanied by physical symptoms associated with anxiety. "Our data from the pharmacological inhibition studies suggest BTK as a novel target for the development of potential clinical treatment of PTSD and anxiety disorders." (PMID 34895246, 2021). "Thereafter, we focused on our primary goal, i.e., Bruton’s Tyrosine Kinase (BTK), an molecule hitherto unrecognized in literature pertinent to PTSD and other anxiety disorder." (PMID 34895246, 2021). "In this context, further studies are required to explore the potential of BTK as a novel target for the treatment of PTSD and anxiety disorders." (PMID 34895246, 2021).
aortic aneurysm and dissection (1 paper, 2025). "Additionally, the inhibition of Bruton’s tyrosine kinase (BTK) has been shown to ameliorate vascular degeneration, dissection, and rupture in models of aortic aneurysm and dissection (AAD)." (PMID 40507607, 2025).
aplastic anemia (1 paper, 2020). Anemia resulting from bone marrow failure (aplastic or hypoplastic bone marrow). "Deficiencies in BTK resulted in the impaired activation and proliferation of autoreactive T cells and ameliorated bone marrow failure (BMF) in aplastic anemia." (PMID 31431692, 2020). "Treatment with acalabrutinib, a selective BTK inhibitor, decreased T-cell proliferation and ameliorated BMF in mice with aplastic anemia." (PMID 31431692, 2020).
aseptic meningitis (1 paper, 2023). Inflammation of the membranes surrounding the brain and spinal cord without a bacterial pathogen. "We reviewed the literature and uncovered the lack of current reports on zanubrutinib or other BTK inhibitor-induced aseptic meningitis." (PMID 37727390, 2023).
Atrophy (1 paper, 2021). Any weakening or degeneration, especially through lack of use. "Additionally, the expression of BTK in IgAN patients with mesangial hypercellularity, endocapillary hypercellularity, segmental glomerulosclerosis, tubular atrophy/interstitial fibrosis, and crescents was significantly higher than IgAN patients without those histological manifestations." (PMID 33389462, 2021).
autoimmune lymphoproliferative syndrome (1 paper, 2025). Autoimmune lymphoproliferative syndrome (ALPS) is a rare, inherited disorder characterized by non-malignant lymphoproliferation, multilineage cytopenias, and a lifelong increased risk of Hodgkin's and non-Hodgkin's lymphoma. "Three patients —one with caspase-8 deficiency and two with BTK gene mutations—were subsequently diagnosed with autoimmune lymphoproliferative syndrome (ALPS) or reactive lymphadenopathy with BMF and were excluded from the analysis." (PMID 40047910, 2025).
autoimmune neurological diseases (1 paper, 2025). "Although there are no clinical studies were performed using BTK inhibitors such as ibrutinib to treat ICH, BTK inhibitors have been used in several clinical trials to treat autoimmune neurological diseases such as MS (NCT04410978, NCT04410991, NCT04411641) and NMOSD (NCT05356858)." (PMID 39744694, 2025).
benign neurofibroma (1 paper, 2021). "Interestingly, expression of CD14 correlated strongly with the expression of BTK in benign neurofibroma (Miller, N = 86) as well as in different NB cohorts except for Hiyama." (PMID 33669187, 2021).
bleeding disorders (1 paper, 2024). "Unfortunately, there is still not a demonstrated cure for CLL, and the necessary chronic exposure to BTK inhibitors can elicit adverse events, e.g., major cardiac or bleeding disorders." (PMID 39664277, 2024).
brain injury (1 paper, 2020). Acute and chronic (see also brain INJURIES, CHRONIC) injuries to the brain, including the cerebral hemispheres, CEREBELLUM, and brain STEM. "Within the mammalian brain, chemical inhibition of the Tec-family kinase BTK increased brain cell survival after ischemic brain injury, an effect attributed to the modification of macrophage activity." (PMID 31958270, 2020).
brain tumors (1 paper, 2022). "Gemistocytes are considered neoplastic GFAP+-p65-Bruton’s tyrosine-kinase+ (BTK+)-expressing astrocytes with a typical cell shape and are found in several brain tumors including GBM." (PMID 35456027, 2022).
chronic neutrophilic leukemia (1 paper, 2021). A rare chronic myeloproliferative neoplasm characterized by neutrophilic leukocytosis. "In addition to AML and MDS, aberrant activation of BTK has been detected in patients of chronic neutrophilic leukemia (CNL) with G-CSFR mutations and these cells show high sensitivity to ibrutinib treatment." (PMID 34778053, 2021).
congenital agammaglobulinemia (1 paper, 2016). An instance of agammaglobulinemia that is present from birth. "Early diagnosis of congenital agammaglobulinemia should be based on clinical symptoms, family history, and molecular analysis of the BTK gene." (PMID 27512878, 2016).
demyelination (1 paper, 2020). "In conclusion, our data establish and highlight the capability of therapeutic BTK inhibition to control disease-driving B-cell–T cell interactions in inflammatory CNS demyelination without permanently removing either cell type." (PMID 32761407, 2020).
diabetic nephropathy (1 paper, 2020). "Here, inhibition of BTK with ibrutinib reduced both NF‐κB and NLRP3 inflammasome activation in the kidney, reduced classical histological markers of early diabetic nephropathy, and protected mice from the development of proteinuria." (PMID 32608058, 2020).
Diarrhoea (1 paper, 2022). "Diarrhoea was another AE found to be associated with the use of BTK inhibitors, which is also often related to inhibition of the EGFR." (PMID 36438789, 2022).
Ecchymosis (1 paper, 2025). A purpuric lesion that is larger than 1 cm in diameter. "While ibrutinib has not been reported to induce similar lesions, ibrutinib itself is associated with an increased risk of bleeding, as common cutaneous toxicities related to Bruton tyrosine kinase inhibitors may commonly include ecchymosis and petechiae development." (PMID 40276727, 2025).
enteropathy (1 paper, 2025). "Although total T-cell numbers remained comparable to pre-transplant levels, their renewed origin and restored BTK expression likely contributed to the clearance of both pathogens and the resolution of enteropathy through effective intestinal cellular immunity." (PMID 40963632, 2025).
epilepsy (1 paper, 2024). A brain disorder characterized by episodes of abnormally increased neuronal discharge resulting in transient episodes of sensory or motor neurological dysfunction, or psychic dysfunction. "We show that the use of some DMTs and a BTK inhibitor appear to be associated with a lower chance of epilepsy." (PMID 39371642, 2024). "In this study, we aimed to explore the association of DMTs for MS and FDA-approved BTK inhibitors (for indications other than MS) with the occurrence of epilepsy using reports from the US Food and Drug Administration Adverse Event Reporting System (FAERS)." (PMID 39371642, 2024). "Our results suggest that the FDA-approved BTK inhibitor ibrutinib, as well as the anti-CD20 monoclonal antibodies including ocrelizumab, ofatumumab, and rituximab, are associated with reduced odds of epilepsy." (PMID 39371642, 2024). "Finally, caution needs to be taken regarding the generalizability of the results about the potential inverse association between ibrutinib and epilepsy in patients with MS, given ibrutinib is used for lymphocytic malignancies, and there is yet no FDA-approved BTK inhibitor for MS." (PMID 39371642, 2024).
Fanconi anemia (1 paper, 2022). Fanconi anemia (FA) is a hereditary DNA repair disorder characterized by progressive pancytopenia with bone marrow failure, variable congenital malformations and predisposition to develop hematological or solid tumors. "Each of these four genes is mutated in a hereditary disease/syndrome, which are the hereditary breast and ovarian cancer syndrome (BRCA1), α-gammaglobulinemia (BTK), Fanconi anemia (FANCA), and spastic paraplegia 4 (SPAST)." (PMID 36075911, 2022).
fibrosis (1 paper, 2023). the formation of excess fibrous connective tissue in an organ or tissue in a reparative or reactive process. "We further explored whether blocking BTK alleviated cardiac fibrosis caused by β-AR." (PMID 37630287, 2023). "Overall, these data indicate that ZB reduces ISO-induced cardiac fibrosis and inflammation by the BTK, STAT3, NF-κB, and PI3K/Akt signaling pathways in vivo." (PMID 37630287, 2023).
gastric lymphoma (1 paper, 2022). An extranodal lymphoma that arises from the stomach with the bulk of the mass located in the stomach. "CARD11 mutations are rare but more frequently found in gastric lymphomas (30%), suggesting BTK resistance." (PMID 36051079, 2022).
glomerulonephritis (1 paper, 2022). A renal disorder characterized by damage in the glomeruli. "In an experimental FcR-dependent, Ab-mediated model of glomerulonephritis, administration of PF-06250112 (an oral BTK inhibitor) at the time of induction reduced proteinuria, supporting the role of inhibition of the BTK signaling pathway in limiting the disease development." (PMID 36294458, 2022).
hearing loss (1 paper, 2020). "In contrast, the other four who had larger deletions expanding from exon 6 in the BTK gene seemed to have gradual psychomotor retardation, speech impairment, and sensorineural hearing loss." (PMID 33013854, 2020).
Hepatitis (1 paper, 2023). Inflammation of the liver. "Recent studies have shown that CLL patients benefit from adjuvanted zoster vaccines, including individuals on chronic BTK inhibition, but that hepatitis B immunization elicited poor or no responses in both treatment-naive and BTK inhibitor treated patients." (PMID 37384638, 2023).
indolent B cell lymphomas (1 paper, 2023). "Inhibitors of phosphatidylinositol 3-kinase (PI3K) and Bruton tyrosine kinase (BTK) represent a recognized option for the treatment of patients affected by indolent B cell lymphomas." (PMID 36675328, 2023).
large cell lymphoma (1 paper, 2023). "The ability of LUX and IB to reduce the phosphorylation of BTK at Y551 was examined in SU-DHL-6 large cell lymphoma cells with and without activation of BCR by a 15 min exposure to anti-IgM." (PMID 36888611, 2023).
Listeria monocytogenes infection (1 paper, 2024). "In contrast, BTK-deficient macrophages display elevated levels of the pro-inflammatory cytokines TNF-α, IL-6, and IL-12 in Listeria monocytogenes infection, suggesting that BTK regulates the extent of the inflammatory response in macrophages in a context-specific manner." (PMID 39518015, 2024).
liver cancer (1 paper, 2017). An epithelial or non-epithelial malignant neoplasm that arises from the liver. "Together, BTK inhibitors may be potential drugs for liver cancer therapy." (PMID 28686599, 2017). "Furthermore, through a bioinformatics (LINCS program) prediction, BTK inhibitors and withaferin A could downregulate DDC expression, suggesting that such drugs could potentially alter the early events of metabolomics of liver cancer cells." (PMID 28686599, 2017). "Furthermore, through a bioinformatics prediction, BTK inhibitors and withaferin A could downregulate DDC expression, suggesting that such drugs could potentially alter the early events of metabolomics of liver cancer cells." (PMID 28686599, 2017).
liver disease (1 paper, 2025). "As another emerging target, Bruton’s tyrosine kinase (BTK) is a critical signaling molecule within the B-cell receptor and other innate immune pathways, with its inhibition now being explored for modulating macrophage function in liver disease." (PMID 41293237, 2025).
lymphadenitis (1 paper, 2021). Acute or chronic inflammation of one or more lymph nodes. "But there were significant difference in phospho-BTK and phospho-CYLD in the non-GCB-DLBCL patient samples (P1–P5) compared with the lymphadenitis patient samples (B1–B5)." (PMID 33827598, 2021).
Lymphadenopathy (1 paper, 2022). Enlargement (swelling) of a lymph node. "Resistance mutations in BTK and PLGC2 were less frequently detected among patients relapsing with lymphadenopathy (40%) compared to those with lymphocytosis (81%) in a prior study." (PMID 36050317, 2022).
macrophage activation syndrome (1 paper, 2020). A complication of rheumatic disease that is caused by excessive activation and uncontrolled proliferation of T lymphocytes and well-differentiated macrophages. "The mechanism of hypercytokine storm from HLH resembling macrophage activation syndrome infers that the absence of BTK can augment inflammation cytokines through Toll-like receptor signaling pathways (TLR4, 7, 8, and 9), possibly driving to the HLH process as two brothers in a previous report." (PMID 33013854, 2020).
mastocytosis (1 paper, 2015). A clonal myeloproliferative neoplasm characterized by the proliferation and accumulation of neoplastic mast cells in one or multiple organs or organ systems. "Given the relative success of PI3K and BTK inhibitors in treating other malignancies, it remains to be seen whether they demonstrate similar efficacy in mastocytosis patients." (PMID 26158763, 2015). "Thus targeting BTK, PI3K, JNK in clinical trials involving mastocytosis patients holds significant promise." (PMID 26158763, 2015).
metabolic syndrome (1 paper, 2019). A cluster of metabolic risk factors for CARDIOVASCULAR DISEASES and TYPE 2 DIABETES MELLITUS. "The results of this computational framework highlight a prominent role of the immune system in metabolic syndrome and suggest a potential use of the BTK inhibitor ibrutinib as a novel pharmacological treatment." (PMID 31740673, 2019).